DUSP6 (dual specificity phosphatase 6)
Diseases named in the same sentence as DUSP6 in open-access papers (continued):
Sharing a sentence is not in itself a finding about the gene and the disease.
Arthritis (1 paper, 2024). Inflammation of a joint. "We next examined whether the deletion of DUSP6 could affect the numbers of T and B cell subsets implicated in arthritis and autoimmunity." (PMID 38974475, 2024). "DUSP6 KO female mice also had significantly lower arthritis score (WT n = 19, DUSP6 KO n = 18, ∗∗∗p < 0.006; ∗p = 0.02)." (PMID 38974475, 2024). "It will be important to characterize the underlying mechanism of the DUSP6 regulation on IL10 and IL6 expression, as well as DUSP6-specific target signaling pathways in arthritis." (PMID 38974475, 2024). "DUSP6 KO mice were protected and had lower arthritis severity scores and lower joint histology damage scores and erosions." (PMID 38974475, 2024). "DUSP6 KO males were protected and had lower arthritis severity scores compared with WT mice." (PMID 38974475, 2024). "But it will be important to examine the role of DUSP6 in neutrophil functions in arthritis." (PMID 38974475, 2024). "The analyses of the median cumulative arthritis scores over time, representing the area under the curve, also revealed significantly lower scores in the combined male + female group (p = 0.0115; Mann-Whitney test), and in the female DUSP6 KO group, compared with WT (p = 0.05)." (PMID 38974475, 2024). "Male and female DUSP6 KO and wild-type (WT) mice were studied in KRN serum-induced arthritis (KSIA) for fourteen days." (PMID 38974475, 2024). "We used the KRN serum-induced arthritis (KSIA) model of RA and showed that DUSP6−/− mice were protected and had a 50% lower maximum arthritis score (p = 0.006) and reduced joint damage than C57BL/6 DUSP6+/+ controls." (PMID 38974475, 2024). "While DUSP6 KO mice were again protected in the KSIA model, the IL10 KO and the double KO mice developed severe disease with arthritis scores higher than those of the C57BL/6 WT mice." (PMID 38974475, 2024). "Following the observation of increased serum levels of IL10, as well as increased frequency of IL10+ cells in the DUSP6 KO mice, we hypothesized that IL10 was mediating the arthritis-protective effect observed in DUSP6 KO mice." (PMID 38974475, 2024). "The dual specificity phosphatase 6 (DUSP6) has been implicated in the regulation of RTK signaling, but never in the context of arthritis and autoimmunity." (PMID 38974475, 2024).
atherosclerosis (1 paper, 2021). A disease characterized by the build-up of fatty material and calcium deposition in the arterial wall resulting in partial or complete occlusion of the arterial lumen. "DUSP-1 and DUSP-6 expression levels are elevated in a number of cardiovascular diseases and DUSP-1 deficient mice are protected from atherosclerosis development." (PMID 34493753, 2021).
B-cell acute lymphoblastic leukemia (1 paper, 2019). A neoplasm of lymphoblasts committed to the B-cell lineage, typically composed of small to medium-sized blast cells. "As far as DUSP6 is concerned, while its ectopic expression reduces cell proliferation in pancreatic and lung cancers, DUSP6 has a pro-oncogenic function in B-cell acute lymphoblastic leukemia." (PMID 31117237, 2019).
benign thyroid neoplasms (1 paper, 2017). "Immunohistochemistry-based technique detection demonstrated that DUSP6 levels are increased in PTCs in comparison with benign thyroid neoplasms." (PMID 28910386, 2017).
brain tumor (1 paper, 2020). "CIC was found to be expressed in several GBM and primary brain tumor-initiating cell (BTIC) lines despite exhibiting increased expression of CIC target genes downstream of MAPK (ETV1/4/5, DUSP6, SPRY4), compared to NHA cells." (PMID 33115448, 2020).
breast tumor (1 paper, 2024). "Further, providing clinical validation for the link between NRG and DUSP6, NRG mRNA was significantly overexpressed in breast tumors with high DUSP6 mRNA expression." (PMID 38886591, 2024). "Indeed, our findings directly support these conclusions as DUSP6 knockout in tumor cells improves survival of mice with intracranial HER2+ tumors and the outgrowth of HER2+ breast tumor cells in a zebrafish intracranial model." (PMID 38886591, 2024).
cardiomyopathy (1 paper, 2022). A disease of the heart muscle or myocardium proper. "Depletions of different DUSPs in mice have shown changes in cardiomyocyte morphology (DUSP8,), or have been linked to protection (DUSP6,) or, in contrast, to increased susceptibility to cardiomyopathy (DUSP1, DUSP4,)." (PMID 36227898, 2022).
Cerebral ischemia (1 paper, 2023). Restriction of arterial blood supply to the brain associated with insufficient oxygenation to support the metabolic requirements of the tissue. "The percentage of nose pokes at the target hole was significantly reduced in DUSP6+/+ mice compared to DUSP6−/− mice after tGCI in both groups, indicating that DUSP6 deficiency reduced the impairment of memory retrieval after cerebral ischemia." (PMID 37175394, 2023). "In this study, we investigated the expression and function of DUSP6 in the context of cerebral ischemia." (PMID 37175394, 2023). "Bonferroni’s multiple comparisons test showed that DUSP6+/+ mice after tGCI had significantly greater latency than naïve DUSP6+/+ mice in locating the target hole on training days 1, 2, and 3, suggesting that cerebral ischemia disrupted spatial memory acquisition and retention." (PMID 37175394, 2023). "However, the role of DUSP6 in cerebral ischemia remains elusive." (PMID 37175394, 2023).
cervical cancer (1 paper, 2025). A primary or metastatic malignant neoplasm involving the cervix. "Furthermore, another recent work supported the tumour suppressor role of DUSP6 in cervical cancer, demonstrating that the protein ribosomal L22-like 1 (RPL22L1) is overexpressed in this type of tumour and is capable of binding and sequestering DUSP6." (PMID 40943262, 2025).
clear cell renal cell carcinoma (1 paper, 2022). "In clear cell renal cell carcinoma, our data convincingly demonstrated a mechanism by which SKA1 promotes tumor metastasis through SAFB-mediated transcriptional repression of DUSP6." (PMID 36462498, 2022).
coronary artery disease (1 paper, 2021). "Also, DUSP-6 seems to be increased in coronary artery disease (p < 0.1), albeit not significantly." (PMID 34493753, 2021).
COVID-19 (1 paper, 2023). A disease caused by infection with severe acute respiratory syndrome coronavirus 2. "The results revealed various diseases from the common DEGs of AKI, CKD, and COVID-19, which include DUSP6, NRIP1, TNFAIP8, S1PR1, and TANK." (PMID 37026010, 2023). "DUSP6, BHLHE40, RASGRP1, and TAB2, the top 4 topological metric hub genes, appear to be pivotal molecular targets of COVID-19, AKI, and CKD." (PMID 37026010, 2023). "Hub genes identified from the protein–protein interaction (PPI) network, including DUSP6, BHLHE40, RASGRP1, and TAB2, are potential therapeutic targets in COVID-19 with AKI and CKD." (PMID 37026010, 2023). "Hence, manipulation of DUSP6 holds great potential for the treatment of acute inflammatory diseases, such as AKI and COVID-19." (PMID 37026010, 2023).
craniosynostosis (1 paper, 2018). Craniosynostosis is defined as the premature fusion of one or more cranial sutures leading to secondary distortion of skull shape resulting in skull deformities with a variable presentation. "Previous work revealed that Dusp6 mutant mice exhibit increased pERK and Erm expression, skeletal dwarfism, craniosynostosis, and hearing loss." (PMID 29544468, 2018).
cutaneous squamous cell carcinoma (1 paper, 2017). "Knockdown of LINC00162 suppresses cell proliferation and cell migration by inhibiting ERK1/2 activity and down-regulating the expression of DUSP6 in cutaneous squamous cell carcinoma." (PMID 28881680, 2017).
dilatation (1 paper, 2022). "In contrast, the Dusp6-deficient hearts had better systolic performance and smaller cardiac dilatation than the WT sibling hearts at 4 weeks after MI, as indicated by better preserved ejection fraction and fractional shortening as well as smaller LV end-diastolic volume and end-systolic volume." (PMID 36335128, 2022).
ductal carcinoma (1 paper, 2011). "Mcs6 human orthologous transcripts that have been reported as differentially expressed between non-diseased breast tissue and ductal carcinoma tissue encode for two phosphatases (DUSP6, PPP1R12A), a proteoglycan (EPYC), a redox regulator (TXNRD1), and two uncharacterized proteins (ALX1, ZDHHC17)." (PMID 21625632, 2011).
dwarfism (1 paper, 2025). "DUSP6 knockout mouse models displayed dwarfism-related skeletal abnormalities." (PMID 40218365, 2025).
epidermoid carcinoma (1 paper, 2023). "Interestingly, shRNA depletion of DUSP6 resulted in up to a 9 h delay in the S phase of epidermoid carcinoma A431 cells after thymidine synchronization." (PMID 37760412, 2023).
Glucose intolerance (1 paper, 2017). Glucose intolerance (GI) can be defined as dysglycemia that comprises both prediabetes and diabetes. "DUSP6 KO mice subjected to HFD for 16 weeks revealed the same glucose intolerance as chow-fed KO mice, i.e. unchanged baseline glucose levels, significantly increased glucose excursions 15 min after a glucose bolus, and a quick normalization of glucose levels with unchanged AUC levels." (PMID 28873424, 2017). "DUSP6 KO mice in our study developed mild glucose intolerance on chow and high fat diet." (PMID 28873424, 2017).
graft versus host disease (1 paper, 2018). An immune system disorder that occurs after allogeneic hematopoietic stem cell transplant and is a reaction of donor immune cells against host tissues. "The inhibition of DOT1L or DUSP6 overexpression in T cells attenuates the development of graft-versus-host disease, while retaining potent antitumor activity in xenogeneic and allogeneic adoptive immunotherapy models." (PMID 29765028, 2018).
hepatitis C virus infection (1 paper, 2017). A viral infection caused by the hepatitis C virus. "Over-expression of DUSP6 is also reported to impair T-cell function in chronic viral infections such as hepatitis C virus infection." (PMID 28642802, 2017).
invasive carcinoma (1 paper, 2015). A carcinoma that is not confined to the epithelium, and has spread to the surrounding stroma. "The expression of DUSP6 is increased in PanINs while it is decreased in invasive carcinoma, which indicates that DUSP6 may be a gatekeeper preventing progression of the precursor lesion into a fully invasive cancer." (PMID 25699241, 2015).
invasive ductal adenocarcinoma (1 paper, 2016). "Overall this data was interpreted as evidence that DUSP6/MKP-3 is associated with progression from early PanINs to invasive ductal adenocarcinoma (PDAC)." (PMID 26791049, 2016).
liver cancer (1 paper, 2025). An epithelial or non-epithelial malignant neoplasm that arises from the liver. "In line with the notion that DUSP4 and DUSP6 act as negative feedback regulators, limiting MAPK signalling to prevent oncogene-induced senescence, their silencing increased cell proliferation and ERK1/2 activation in liver cancer cells." (PMID 40943262, 2025).
liver cirrhosis (1 paper, 2022). "Associations between increased levels of DUSP6 and HCC or liver cirrhosis have been reported." (PMID 36386790, 2022).
malignant peripheral nerve sheath tumor (1 paper, 2021). Malignant peripheral nerve sheath tumor (MPNST) is a rare and often aggressive soft tissue sarcoma occurring in a wide range of anatomical sites. "DUSP6 is proved to be involved in biological functions, such as M2 macrophage polarization, immunologicalreaction, aggressive malignant peripheral nerve sheath tumors (MPNSTs) growth, and T cell receptor sensitivity." (PMID 34475393, 2021). "Moreover, DUSP6, along with DUSP1, suppresses malignant peripheral nerve sheath tumor (MPNST) growth via JNK signaling." (PMID 34475393, 2021).
metastatic tumor (1 paper, 2020). "In addition, we compared DUSP6 protein levels between the primary and metastatic tumors within the same patient (n = 19)." (PMID 32159851, 2020). "It showed that DUSP6 protein levels of metastatic tumors were positively correlated with those of primary tumors (R = 0.8666, p < 0.0001), and DUSP6 expression was maintained in the metastatic tumor (linear regression equation: y = 0.9359x − 0.5681)." (PMID 32159851, 2020).
multiple sclerosis (1 paper, 2019). A progressive autoimmune disorder affecting the central nervous system resulting in demyelination. "The fact that DUSP6 increases in rat optic nerves exposed to excitotoxicity and in rat optic nerves of patients with multiple sclerosis suggests that DUSP6 overexpression might be a risk factor of vulnerability in early stages of this disease." (PMID 31018603, 2019).
myelofibrosis (1 paper, 2022). A partial or complete replacement of the bone marrow stroma by fibrous tissue. "This dovetails nicely with ongoing work suggesting DUSP6 contributes to JAK2 inhibitor resistance and may be a therapeutic target in myelofibrosis, an unexpected finding given DUSP6 inhibition would in theory enhance ERK activity." (PMID 35082276, 2022).
nonalcoholic steatohepatitis (1 paper, 2024). "Moreover, M. formatexigens secreted the methylated amino acid Nε-methyl-L-lysine, an enriched cecal metabolite in Dusp6 knockout mice that reduces adiposity and ameliorates nonalcoholic steatohepatitis in mice." (PMID 38480743, 2024).
occlusive vascular disease (1 paper, 2023). "Our findings propose DUSP6 as a potential target for the development of therapeutic strategies for occlusive vascular disease." (PMID 38138967, 2023).
prostate adenocarcinoma (1 paper, 2018). "Rs10896449 likely interacts with DUSP6, a gene that when knocked down promotes the invasion and proliferation of LNCap human prostate adenocarcinoma cells." (PMID 29560112, 2018).
prostate tumors (1 paper, 2016). "Compared to the primary prostate tumors, mRNA level of NFKBIA, DUSP6, PLCB3, and SMAD4 are lower in metastatic prostate tumors, while mRNA level of RELA and SNAI1 exhibit opposite trend." (PMID 27191743, 2016). "On the other hand, mRNA levels of ROR2, NFKBIA, DUSP6, PLCB3, and SMAD4 are lower in metastatic prostate tumors as compared to primary prostate tumors." (PMID 27191743, 2016).
psoriasis (1 paper, 2021). An autoimmune condition characterized by red, well-delineated plaques with silvery scales that are usually on the extensor surfaces and scalp. "By regulating cell death and differentiation in both immune cells and epidermal keratinocytes, DUSP6 represents a credible therapeutic target for 311 nm UVB in psoriasis." (PMID 33812333, 2021).
renal tumor (1 paper, 2018). "Highly expressed p16 and DUSP6 may have contributed to these results, which maintained MA as a benign renal tumor." (PMID 30111351, 2018).
retinal degeneration (1 paper, 2022). Degeneration of the retina. "Collectively, our findings show that the inhibition of DUSP6 protects against retinal degeneration through promoting autophagic flux under NaIO3-induced oxidative stress." (PMID 35052838, 2022). "To identify the role of DUSP6 in response to oxidative stress in this retinal degeneration model, we collected eyeballs from the NaIO3-treated mice at different time points and examined the DUSP6 protein expression in the retina after NaIO3 treatment." (PMID 35052838, 2022). "However, the treatment effect of NaIO3 on the expression of DUSP6 and the role of DUSP6 in autophagic flux in retinal degeneration remain unclear." (PMID 35052838, 2022). "In the model of retinal degeneration induced by the exposure of ARPE-19 cells to oxidized low-density lipoprotein (oxLDL), DUSP6 was found to be elevated in response to oxLDL treatment." (PMID 35052838, 2022). "We also studied the impact of a DUSP6 inhibitor, (E/Z)-BCI hydrochloride (BCI), on the regulation of the ERK1/2 pathway in retinal degeneration models." (PMID 35052838, 2022). "Treatment with the DUSP6 inhibitor BCI modulates the autophagy activity and provides novel therapeutic help to restore autophagic flux and prevent retinal degeneration induced by oxidative stress." (PMID 35052838, 2022). "In the present study, we investigated whether the regulation of DUSP6 could rescue retinal degeneration via the ERK1/2 autophagy pathway in both in vivo and in vitro retinal degeneration models through sodium iodate treatment." (PMID 35052838, 2022). "In brief, we demonstrated that the DUSP6/ERK axis was upregulated in the mouse retina under NaIO3-induced oxidative stress, and this axis may play a critical role in the regulatory mechanism of retinal degeneration." (PMID 35052838, 2022).
rhabdomyosarcoma (1 paper, 2025). A rare aggressive malignant mesenchymal neoplasm arising from skeletal muscle. "Thus, we hypothesize that other putative mechanisms, such as DUSP6-mediated dephosphorylation of DRP1 at S616, may also contribute to the regulation of DRP1 phosphorylation in rhabdomyosarcoma." (PMID 39643272, 2025).
serous adenocarcinoma (1 paper, 2019). An adenocarcinoma that is characterized by the presence of papillary patterns and cellular budding. "To verify the clinical relevance of our findings, we performed immunohistochemistry of DUSP6 in an EOC tumor microarray and compared levels in serous adenocarcinoma samples (n=40) to levels in normal adjacent tissue (NAT; n=7)." (PMID 31164954, 2019).
T-cell leukemia (1 paper, 2015). A malignant disease of the T-lymphocytes in the bone marrow, thymus, and/or blood. "As mechanism of action, miR181 targets PTPN, DUSP5, and DUSP6, resulting in PI3K/AKT activation and tumorigenesis in murine T-cell leukemia." (PMID 26436088, 2015).
T-LGL leukemia (1 paper, 2022). "We identified that the overexpression of one particular miRNA, miR-181a, which results in hyperactive STAT3 and ERK1/2 by decreasing SOCS3 and DUSP6 expression in T-LGL leukemia patient cells, eventually leads to resistance to FAS-mediated apoptosis." (PMID 34873301, 2022). "By using TL1, a human T-LGL cell line, we could show that miR-181a is an actor in T-LGL leukemia, driving STAT3 activation by SOCS3 inhibition and ERK1/2 phosphorylation by DUSP6 inhibition and verified this mechanism in an independent cell line." (PMID 34873301, 2022).